MEN1 (menin 1)
Diseases named in the same sentence as MEN1 in open-access papers (continued):
Sharing a sentence is not in itself a finding about the gene and the disease.
pancreatic neuroendocrine tumor (continued). "MEN1 is characterized by the occurrence of parathyroid, pituitary and pancreatic neuroendocrine tumors (PanNETs)." (PMID 35941657, 2022). "Pancreatic neuroendocrine tumor is the second most common MEN1-related tumor and is present in 30–80% of MEN1 patients; however, post-mortem studies showed a higher prevalence of 80–100%." (PMID 33807230, 2021). "Nevertheless, given the rarity of these thymic tumors, pancreatic NET are the main focus of therapeutic interventions to improve MEN1 mortality." (PMID 33716975, 2021). "In NET G3, which is most frequently occurring in the pancreas, most alterations were also seen in pancreatic primaries, including mutations in MEN1 (33%), ATRX (25%) and DAXX (25%; within the subgroup of pancreatic NET G3)." (PMID 34647903, 2021). "At genetic diagnosis of MEN1, she harbored three of the most common MEN1 tumors: parathyroid adenomas, pancreatic NETs, and prolactinoma." (PMID 34160414, 2021). "We report a 32-year-old female who had 3 common MEN1 tumors; in particular, she had various kinds of pancreatic NETs, 3 insulinomas, 1 glucagonoma, and 1 gastrinoma, simultaneously." (PMID 34160414, 2021). "We also analyzed LOH of PHLDA3 and MEN1, two tumor suppressor genes frequently inactivated in pancreatic NETs." (PMID 30787304, 2019). "Recently, we reported that in pancreatic NET patients, a loss of heterozygosity (LOH) in PHLDA3 was associated with poorer prognosis, and that LOH of both PHLDA3 and MEN1 was frequently observed." (PMID 30787304, 2019). "Pancreatic neuroendocrine tumors (pNETs) are estimated to occur in 30–80% of patients with MEN1, and in up to 80–100% of patients in postmortem studies." (PMID 31263451, 2019). "In pancreatic neuroendocrine tumors (PanNETs) ATRX, DAXX, and MEN1 are commonly mutated (A-D-M mutant PanNETs)." (PMID 30315258, 2018). "Pancreatic NETs (PanNETs) have been among the most studied, and research so far has outlined a series of recurring features, as inactivation of MEN1, VHL, TSC1/2 genes and hyperactivation of the PI3K/mTOR pathway." (PMID 29321190, 2018). "Since nonfunctioning pancreatic NET's also occur from a young age, MEN1 testing should perhaps not only be limited to patients with insulinomas before the age of 20, but recommended for all patients with pancreatic NET's before this age." (PMID 30254610, 2018). "The ENETS consensus guidelines for the management of pancreatic NET's recommend testing for MEN1 in patients presenting with insulinoma before the age of 20, in addition to testing of patients with multiple pancreatic NET's at any age." (PMID 30254610, 2018). "Recent genetic studies have highlighted that alterations in MEN1, chromatin remodeling genes, and mammalian target of rapamycin (mTOR) pathway genes are the most frequent molecular events identified in pancreas neuroendocrine tumors (pNETs)." (PMID 29212165, 2017). "Recently, pancreatic NETs were characterized as having recurrent somatic mutations in MEN1, DAXX, ATRX, TSC, and PTEN on the basis of exome sequencing of 10 pancreatic NETs." (PMID 26684240, 2016). "Immunofluorescence (IF) and western blot assays were used to identify increased DNMT1 protein levels in MEN1-parathyroid tumors, mouse pancreatic endocrine tumors from Men1 KO mice, and mouse parathyroid tumors from a different Men1 KO mouse model." (PMID 26871472, 2016). "In patients with MEN1 mutations, the most frequently encountered features are PHPT, pancreatic endocrine tumors and pituitary adenomas, but adrenal cortical adenoma is also found at a frequency of around 9–45 %." (PMID 24343173, 2015).
pancreatic neuroendocrine tumor (continued). "According to the MEN consensus panel, the clinical diagnosis of this syndrome is based on the concomitant occurrence of at least two of the three MEN1-related endocrine tumours (parathyroid adenoma, pituitary adenoma, pancreatic NET)." (PMID 25824098, 2015). "Taking into account the main MEN1-related manifestations, 42 patients (76%) had primary hyperparathyroidism, 23 (42%) pituitary adenoma, 33 (60%) pancreatic NETs, 2 (4%) thoracic NET and 7 (13%) adrenocortical tumour." (PMID 25824098, 2015). "Pancreatic neuroendocrine tumors occur as a part of MEN1 syndrome, von Hippel-Lindau syndrome, and neurofibromatosis type 1, while tumors in the stomach have been found in MEN1." (PMID 25525544, 2014). "We report a case of a female patient who presented with primary hyperparathyroidism (pHPT) and a GHRH- and insulin cosecreting pancreatic NET (pNET) and genetically confirmed multiple endocrine neoplasia type 1 (MEN1), within an undiagnosed family with various MEN1-related NETs." (PMID 42007244, 2026). "Nonetheless, late-onset manifestations of MEN1, such as asymptomatic pancreatic neuroendocrine tumors in patients over 70 years old, have been documented, and low-penetrance RET mutations (e.g., K666N) have been associated with delayed MEN2 diagnoses and milder phenotypes." (PMID 40525079, 2025). "MEN1, caused by mutations in the MEN1 gene, classically leads to parathyroid, pituitary, and pancreatic neuroendocrine tumors, but adrenal tumors—predominantly non-functioning—occur in up to 40% of patients." (PMID 41007858, 2025). "Since non-functioning pancreatic NETs associated with MEN1 tend to be multifocal and have a low risk of progression, surgery is generally reserved for lesions greater than 1–2 cm in size with growth." (PMID 39941746, 2025). "All these characteristics make MEN1-related pancreatic NETs highly sensitive to SSA treatment." (PMID 37581846, 2024). "Furthermore, there are approximately 40% of pancreatic NETs with mutations in DAXX/ATRX and MEN1, in addition to alternative lengthening of telomeres (ALT), a phenomenon not observed in NECs." (PMID 39382626, 2024). "We present a case with initial presentation of neuroendocrine tumor of pancreas whose ancillary findings on 68 Ga-DOTATATE positron emission tomography-computed tomography helped in raising suspicion of MEN1, which was confirmed on genetic testing and family history." (PMID 38152096, 2023). "The most frequent gene alterations in pancreatic NETs were MEN1 and DAXX/ATRX." (PMID 37387515, 2023). "However, we detected it in a proband with a MEN1 diagnosis from the age of thirteen (pancreatic NET, pituitary microadenoma, and collagenomas on her back and her head) and in his father, with adult-onset pancreatic NET and adrenal adenoma." (PMID 37761922, 2023). "By comparing the clinical features of probands with NETs with and without variants in MEN1, pancreatic NET was overrepresented in MEN1 positive patients (4/4, 100%) but recurred also in MEN1 negative cases (12/18, 66.7%) (p > 0.05)." (PMID 37761922, 2023). "This is especially crucial regarding non-functioning pancreatic neuroendocrine tumors, which are not developed in Men1 knockout mice but serve as the main cause of MEN1-related mortality in patients." (PMID 34769484, 2021). "Alterations in the normal epigenetic regulation of gene transcription (histone modification and/or DNA methylation), following the loss of wild type menin activity, have been demonstrated to play an important role in the progression of MEN1 pancreatic neuroendocrine tumors." (PMID 34298972, 2021).
pancreatic neuroendocrine tumor (continued). "Despite substantial improvement of the overall survival of patients with MEN1, gastroenteropancreatic neuroendocrine tumors, malignant nonfunctioning pancreatic neuroendocrine tumors in particular, remain associated with increased morbidity and mortality." (PMID 30990521, 2019). "The MEN1 pancreas of the adolescent gene carrier frequently contain diffusely spread pre-neoplasias and microadenomas, progressing to macroscopic and potentially malignant pancreatic neuroendocrine tumors (P-NET), which represents the major death cause in MEN1." (PMID 29335487, 2018). "Other studies in patients with MEN1-related pancreatic NETs suggest that DAXX/ATRX mutations are not driver mutations, but rather later events in the pathogenesis of NET development." (PMID 29255447, 2017). "Thus, the apoptotic rate was more than 2-fold higher in pancreatic NETs and more than 6-fold higher in pituitary NETs of pasireotide-treated Men1+/− mice." (PMID 26990064, 2016). "The rate of apoptosis in the pancreatic and pituitary NETs was assessed by TUNEL analysis, and in pancreatic NETs the mean (±SEM) apoptosis rate in pasireotide-treated Men1+/− mice was significantly higher than that in PBS-treated Men1+/− mice (0.42 ± 0.05 vs 0.19 ± 0.03%; P < .001)." (PMID 26990064, 2016). "Thus, in pancreatic NETs the mean (±SEM) proliferation rate in pasireotide-treated Men1+/− mice was significantly lower than that in PBS-treated Men1+/− mice (0.35 ± 0.03 vs 0.78 ± 0.08% per day; P < .0001)." (PMID 26990064, 2016). "Insulinoma is one of the pancreatic NETs arising in the setting of MEN1." (PMID 27572829, 2016). "Endoscopic ultrasound (EUS) constitutes the most sensitive imaging method for the detection of small pancreatic endocrine tumours in asymptomatic MEN1 patients (sensitivity > 75%), while the combination of EUS with Octreoscan scintigraphy, increases the pancreatic tumoural detection rate to 90%." (PMID 21266030, 2011). "Additionally, pancreatic NETs are uncommon in MEN1, affecting less than 2% of patients." (PMID 39201946, 2024). "In addition to pancreatic NETs, individuals with MEN1 may also develop NETs in other parts of the body, including the thymus, lungs, and gastrointestinal tract." (PMID 37761922, 2023). "Moreover, we excluded genetic predisposition syndromes, knowing that therapeutic management is different in these patients who may have multiple NETs in the same organ, such as pancreatic NETs in MEN1 patients." (PMID 36672462, 2023). "miR-155, whose biogenesis is positively regulated by menin, had been previously showed to be s among the top downregulated miRNAs in pancreatic neuroendocrine tumors, and its downregulation could have a role also in MEN1 tumorigenesis of the endocrine pancreas." (PMID 34298972, 2021). "Interestingly, the RASSF1A gene promoter was also shown to be hypermethylated in about 98% of MEN1 neuroendocrine tumors of the pancreas, suggesting the epigenetic inactivation of this gene as a common pathway of MEN1 loss-driven tumorigenesis in target endocrine tissues." (PMID 34681865, 2021). "Pancreatic neuroendocrine tumors (PNETs) account for 1 to 2% of all pancreatic tumors and most of them are sporadic and non-functioning, 5–7% arise within inherited syndromes, including MEN1, Von-Hippel Lindau (VHL) syndrome, neurofibromatosis type 1 (NF1), and tuberous sclerosis." (PMID 33384663, 2020). "However, in addition to determining which other conditions to seek in a patient who carries the MEN1 gene, there is emerging evidence that genotype may impact to an extent on the aggressiveness of the pancreatic NETs." (PMID 28965289, 2017).
pancreatic neuroendocrine tumor (continued). "Both the mutations in MEN1 and DAXX/ATRX suggest that targeting these epigenetic mechanisms with small molecule compounds may be a viable approach to developing new therapeutics for pancreatic NETs." (PMID 29255447, 2017). "In addition, our results suggest that pasireotide may inhibit the development of pancreatic NETs in Men1+/− mice, thereby suggesting that it may also have a chemopreventative role in the treatment of MEN1-associated NETs." (PMID 26990064, 2016). "The heritability of MEN1 alterations among siblings of patients with MEN1-related lung NET and pancreatic NET is lower compared with other NET types (pituitary, adrenal, thymic), though the reason for this is unclear." (PMID 40026252, 2025). "In this cohort of patients, the sensitivities and specificities of VHL and MEN1/LOH alterations were 71% and 100% for SCNs and 68% and 98% for pancreatic neuroendocrine tumors, respectively." (PMID 36832193, 2023). "Clinical syndromes of MEN1 include PHPT, pancreatic neuroendocrine tumors, and anterior pituitary adenomas." (PMID 37795364, 2023). "Hallmarks of NET G1/G2 are loss of chromosome 18, inactivation of CDKN1/APC, and gain of chromosomes 4, 5, and 14 in NET of the small intestine and inactivation of MEN1/chromosome 11, DAXX/ATR, and PTEN/TSC2 in pancreatic NET." (PMID 33228231, 2020). "The most common primary tumors in our MEN1 and MEN2 patients with liver metastases were of pancreatic neuroendocrine tumor (70%, 7/10) und medullary thyroid carcinoma (100%, 15/15) origin, respectively." (PMID 30817772, 2019). "Most MEN1-related gastrinomas (>80%) are found in the duodenum, often with non-functioning pancreatic NETs, complicating diagnosis and treatment." (PMID 39201946, 2024). "Recent systematic endoscopic ultrasonography (EUS) studies in MEN1 individuals devoid of pancreatic symptoms have unveiled that 55% harbor non-functioning pancreatic NETs." (PMID 39201946, 2024). "If the genetic investigation for MEN1 and MEN4 starts with a diagnosis of pancreatic NET, at least three other conditions need to be encountered to suggest the diagnosis of an inherited syndrome, including age, multifocality, endocrine syndrome, and more importantly, other MEN1 manifestations." (PMID 37761922, 2023). "This differentiation capacity is of the greatest interest for considering the clinical picture of MEN1 patients suffering from multiple gland parathyroid hyperplasia, along with non-functioning pancreatic neuroendocrine tumors." (PMID 34769484, 2021). "Furthermore, the gene panel is restricted to 73 genes failing to test for MEN1, ATRX or DAXX, which are clinically important in pancreatic NET." (PMID 32477464, 2020). "The five patients who had true positive elevated plasma somatostatin concentrations all had pancreatic NETs, but none of them had confirmed MEN1." (PMID 33391185, 2020). "In a case report on one patient with metastatic pancreatic NET G−3, the whole-genome sequencing of liver metastases exhibited a TSC1-disrupting fusion, showed a novel CHD7–BEND2 fusion, but lacked any somatic variants in ATRX, DAXX, and MEN1." (PMID 32492939, 2020). "Pancreatic NETs (eg, gastrinomas, insulinomas and nonfunctioning tumors) occur in greater than 40% of patients with MEN1, and pituitary NETs (eg, prolactinomas, somatotrophinomas and corticotrophinomas) occur in greater than 35% of patients after the third decade of life." (PMID 26990064, 2016).
pancreatic neuroendocrine tumor (continued). "The main finding of the study confirms that pancreatic NETs and no other NET sites represent a starting point for a possible MEN1 or MEN4 syndrome." (PMID 37761922, 2023).
insulinomas (109 papers, 2010 to 2026). "Compared to our results, where insulinoma was associated with MEN1 in 35.3% of cases, previous studies estimated the association at 4 to 10%." (PMID 40941664, 2025). "At the genetic level, these tumour subtypes can differ, for example, MEN1 mutations are rarely seen in insulinomas but occur in greater than 40% of NF‐PNETs." (PMID 39579056, 2025). "In this case, we focus exclusively on functional insulinomas, specifically those associated with MEN1." (PMID 40406452, 2025). "The higher recurrence rate of insulinomas in MEN1 patients is primarily due to the genetic predisposition to multiple and recurrent tumors, the presence of multicentric disease, and ongoing pancreatic islet cell hyperplasia." (PMID 40941664, 2025). "This necessitates careful long-term monitoring and often a more comprehensive treatment approach in MEN1-associated insulinomas." (PMID 40941664, 2025). "Gastrinomas, non-functioning pancreatic polypeptide-secreting tumors (PPomas), insulinomas, glucagonomas, and vasoactive intestinal polypeptidomas (VIPomas) constitute the spectrum of NETs associated with MEN1, with varying degrees of penetrance." (PMID 39201946, 2024). "Given the patient’s concurrent presentation with an insulinoma and hyperparathyroidism, we conducted screening for MEN1-associated disease phenotypes and genetic testing." (PMID 39371924, 2024). "The vast majority of patients in both groups had sporadic benign insulinomas (84% group 1 and 75% group 2), followed by MEN1-associated benign insulinomas (13% and 12%), only 4 patients (6.6%) had malignant insulinomas." (PMID 37386194, 2023). "Comparative analysis of the clinical features in pediatric patients with sporadic vs. MEN1-associated insulinoma." (PMID 37152923, 2023). "A somatic MEN1 mutation is also found in the sporadic counterparts of MEN1 tumors: parathyroid adenoma (21%), gastrinoma (33%), insulinoma (17%), and bronchial carcinoid (36%)." (PMID 37761922, 2023). "Of those 61 insulinomas, 49 (80%) were sporadic benign, 8 (13%) benign MEN1-associated insulinomas, and 4 (7%) sporadic malignant insulinomas." (PMID 37386194, 2023). "A similar study was published in 2003, where embryonically heterozygous MEN1 mice were shown to develop insulinomas and glucagonomas in addition to many other MEN1 deficient associated tumor types." (PMID 37568572, 2023). "We compared main clinical characteristics in children with sporadic insulinomas (n=13) and those with pathogenic variants in the MEN1 gene (n=8)." (PMID 37152923, 2023). "It was previously reported that β cell-specific, Men1-deficient mice that lack exons 3–8 or exon 3 develop functional insulinomas with significantly elevated levels of serum insulin levels." (PMID 37679316, 2023). "We identified patients diagnosed with MEN1-associated insulinoma based on endocrinological, radiological, and pathological examinations, and subsequently analyzed their clinical data." (PMID 35698198, 2022). "Approximately 40% of those MEN1 mutations carriers develop PNETs, and 10% of those patients have insulinoma." (PMID 35954231, 2022). "Our case demonstrates MEN1-associated low-grade insulinomas along with higher 68Ga-DOTATATE tracer uptake, which is significant in the proper diagnosis of MEN1-associated low-grade insulinomas with SSTR expression." (PMID 36042606, 2022). "A study revealed that an α-cell specific mutation of Men1 resulted in the increased self-proliferation and the trans-differentiation of α-cells into insulin-positive cells, which subsequently developed into insulinoma." (PMID 35954231, 2022). "In conclusion, we present a rare case of MEN1-associated tumors with low-grade insulinoma and parathyroid and pituitary tumors, which showed MEN1 associated low-grade insulinomas along with higher 68Ga-DOTATATE tracer uptake." (PMID 36042606, 2022). "Studies have reported 68Ga-exendin-4 PET/CT as a valuable and credible imaging technique to distinguish MEN1-associated insulinomas." (PMID 36042606, 2022).